HDAC2 (histone deacetylase 2)
Diseases named in the same sentence as HDAC2 in open-access papers (continued):
Sharing a sentence is not in itself a finding about the gene and the disease.
cancer (continued). "We also performed real-time PCR (RT-PCR) with cDNAs from human STS samples and analyzed the clinical significance of class I HDAC expression including HDAC1, HDAC2 and HDAC3, in 49 patients with different subtypes of STS treated at our cancer center." (PMID 33637599, 2021). "The Cancer Genome Atlas (TCGA) dataset analysis revealed that HDAC4, HDAC7 and HDAC9 as well as HDAC class I members HDAC1 and HDAC2 is significantly correlated with patient survival." (PMID 31635225, 2019). "The immunohistochemistry (IHC) findings for each of the cancers showed that neoplastic cells were heterogenous in their nuclear and cytoplasmic expression of MYC, HDAC2 and TFE3." (PMID 31399583, 2019). "As specific HDAC inhibitors are developed for use in cancer and in various immune and neurological diseases, analysis of their impact on global and specific effects of HDAC1 and HDAC2 should be considered." (PMID 30926862, 2019). "Single knockdown of HDAC1, HDAC2, HDAC3, LSD1, DNMT1, and EZH2 generated different effects of neuron-like differentiation in cell lines of different cancer types." (PMID 31130994, 2019). "Western blot results showed that HDAC1, HDAC2, and HDAC3 expression change between cancer, and adjacent tissue was consistent with the B7-H1 level change in 8 (66.7%), 9 (75.0%), and 9 (75.0%) cases, respectively." (PMID 30537988, 2018). "The best characterised and probably biologically most relevant HDAC in human cancers are class I isoforms HDAC1, HDAC2, and HDAC3." (PMID 28785170, 2017). "A recent study using 115 ovarian tumour tissues confirmed that expression of nuclear HDAC1, HDAC2 and HDAC3 proteins increased stepwise in benign, borderline and malignant tumours." (PMID 26560874, 2016). "The role of individual histone deacetylases (HDACs) in the regulation of cancer cell proliferation was investigated using siRNA-mediated knockdown (HDAC1, HDAC2, HDAC3, HDAC4 and HDAC7) in HeLa cells." (PMID 26560874, 2016). "For example, overexpression of HDAC1, HDAC2, HDAC4, HDAC6, and HDAC7 has been observed in various cancers." (PMID 27902771, 2016). "Previous studies have demonstrated that the class I and II histone deacetylases (HDACs), including HDAC1, HDAC2, HDAC3 and HDAC4, repress p21 expression in multiple human cancers." (PMID 26098774, 2015). "Both HDAC2 and HDAC4 were chosen for this study because the work of others has revealed abnormal levels of these proteins in many types of cancer." (PMID 21507255, 2011). "The reduced viability that we observe upon individual HDAC1, -2 and -3 knockdown has been published on class I HDAC KD in cancer cells, especially via proliferation for HDAC1 and -3, and via apoptosis for HDAC2." (PMID 18789133, 2008). "Although it is primarily observed in cancer cells, deacetylation of PD-L1 by HDAC2 triggers its nuclear translocation without cleavage, where it regulates immune-response genes." (PMID 41446247, 2025). "Also, the oncogenic activity of MYC is significantly induced by HDAC2, suggesting the potential benefits of applying HDAC inhibitors in the prevention and treatment of Myc-driven cancers." (PMID 39063083, 2024). "To date, however, HDAC2 deregulations in CRC progression have not been investigated as drivers of cancer." (PMID 37046620, 2023). "In addition to the METTL14/miR-99a-5p/TRIB2 axis, TRIB2 activates HDAC2 and inhibits HDAC2 (Ser394) phosphorylation through the Akt/mTOR/S6K1 signal pathway in ESCC, thus inhibiting cancer stemness and improving radiation resistance of ESCC cells." (PMID 37522921, 2023). "Although HDAC2-targeting inhibitors have shown some promising anti-cancer effects, clinical trials have not led to the discovery of successful anti-cancer drugs." (PMID 36968022, 2023).
cancer (continued). "Notably, the dual-specificity inhibitor domatinostat (4SC-202) targeting both HDAC1/HDAC2 and LSD1 catalytic activities exhibits anti-tumorigenic effects in various cancer models." (PMID 37878419, 2023). "Several HDACs can act to deacetylate a certain histone in different forms of cancer: H3K9 (HDAC3), H3K14 (HDAC1, HDAC3), H3K56 (HDAC1, HDAC2), H4K5 (HDAC1, HDAC2, HDAC3), H4K8 (HDAC1, HDAC2), H4K12 (HDAC1, HDAC2, HDAC3), and H4K16 (SIRT1, SIRT2, HDAC1, HDAC2, HDAC3)." (PMID 36614156, 2022). "In conclusion, we hypothesize that the upregulated HDAC2 in NPC induced cell cycle disorders by regulating BUB1B, and ultimately promotes the development of cancer." (PMID 36577966, 2022). "The negative effect of Pirh2 on both HDAC1 and HDAC2 levels was demonstrated in several human cancer cell lines including MCF7, HCT116, H1299 and others which apparently indicates the universality of Pirh2-dependent regulation of these histone deacetylases." (PMID 35563824, 2022). "Overexpression of HDAC1, HDAC2, HDAC3, and HDAC6 has been reported in different cancers." (PMID 35096000, 2021). "Literature precedents underscores the association of gene expression silencing with HDAC1/2 and LSD1 enzymatic activities within the CoREST complex (HDAC complex that includes HDAC1, HDAC2, the scaffolding protein CoREST, and LSD1) that contributes to cancer and other diseases." (PMID 33840388, 2021). "Additionally, several studies indicated that the degradation of HDAC2 is one of the anticancer actions of VPA and that knockdown of HDAC2 enhances the sensitivity of GBM cancer cells to TMZ." (PMID 34660288, 2021). "Supported by a recent research, HDAC2 expression is elevated in ESCC which is closely connected with clinical stage and lymph node metastasis, and HDACs inhibition disrupts ESCC cell progression, ameliorates cancer stemness and impedes tumorigenicity in mice." (PMID 33926524, 2021). "However, when grouping benign and LG malignant SGT cases together, staining intensity for HDAC-2 and HDAC-6 successfully differentiated HG malignant from benign plus LG malignant tumors (p = 0.017 and p = 0.028, respectively)." (PMID 33799478, 2021). "We identified three hub genes (HDAC2, SMARCA4, and FOS) by PPI analysis that previous studies have suggested may be crucial in cancer development." (PMID 32391054, 2020). "An anomalous histone acetylation, and consequently an alteration in the expression of HDACs, is related to cancer Likewise, an overexpression of HDAC1 and HDAC2 has been found in LC, and HDAC8 knockdown leads to the inhibition of cell proliferation in lung and other types of cancer." (PMID 30759767, 2019). "Taken together, our results indicate that HDAC1 and HDAC2 positively regulate activation of the FA pathway and that cellular sensitivity to ICL-inducing agents, which are widely used in cancer chemotherapy, may be increased via HDAC1/2 inhibition." (PMID 29100324, 2017). "The level of histone acetylation, however appears to be independent of the deacetylating role of HDAC2 and possibly HDAC2 expression represses transcription factors activation which controls cancer cell death and promotes drug resistance." (PMID 27283986, 2016). "Given their deregulation in cancer HDAC1 and HDAC2 are important therapeutic targets." (PMID 25970771, 2015). "While the up-regulation of HDAC2 has previously been shown by immunohistochemistry in several cancers, HDAC2 expression has never been described in early field carcinogenesis." (PMID 23724067, 2013). "Vorinostat and Flavopiridol are anti-cancer agents involving the HDAC1, HDAC2 and CDK1 genes." (PMID 24564241, 2013). "In addition, six of the frequently hypermethylated genes, i.e., CCND1, COL4A2, HDAC2, AXIN2, ABL1 and GLI2, are included in the pathways in cancer map from the KEGG database." (PMID 22159500, 2012). "Interestingly, HDAC10 alone was down-regulated in HCC827 cells, but there was no change observed in HDAC2 or HDAC4 in either cancer cell line." (PMID 40941018, 2025).
cancer (continued). "Therefore, MYB, HDAC2, and FOXA2 are master regulators in controlling the Boolean GRN model toward an enterocyte state and could be effective targets for cancer treatment." (PMID 39661721, 2025). "Apart from molecular targets expressed in cancer cells of the three types of programs, CD52, CDK6, HDAC2, and PIGF were specifically expressed in inflammatory or EMT meta programs, indicating that drugs against these targets may respond in specific cancer cell subpopulations." (PMID 38944814, 2024). "The therapeutic target genes, such as CDK6, HDAC2 and PIGF, exhibited enhanced expression levels in the EMT meta program, confirming that drugs targeting these genes may have significant therapeutic responses in such cancer cell subpopulations." (PMID 38944814, 2024). "Extensive studies on the HDAC2 interactome might produce HDAC2-selective chemical/peptides with anti-cancer activities without off-target effects." (PMID 36968022, 2023). "Additionally, HDAC2, MCM7, and PTTG1 have also shown potential for treating cancers." (PMID 38001498, 2023). "Homozygous inactivation of HDAC2 occurs in sporadic CRC with MSI and hereditary nonpolyposis colon cancer syndrome, suggesting that these tumors may develop in the absence of HDAC2, a hypothesis that could have major implications for cancer therapy." (PMID 37046620, 2023). "Also the in silico studies proved that the docking score of the compound suggests the interaction of the compound which could tightly regulate key target genes controlling cancer like ER, EGFR kinase, EGFR-cSRC, HDAC-2, PARP-1 and BRAF." (PMID 35059624, 2022). "Interestingly, although HDAC1 and HDAC2 suppress lymphomagenesis in a dosage-dependent manner, complete inactivation of HDAC1 and HDAC2 abrogates lymphomagenesis as some level of HDAC activity is required for cancer cell vulnerability." (PMID 35887172, 2022). "Furthermore, the search for CK2 substrates in the CIGB-300 interactome revealed that the peptide is able to interact with substrates playing central roles in cancer cell physiology, such as protein DEK, G3BP1, HDAC2, DNA topoisomerase 1 and 2-alpha, and others with oncogenic potential." (PMID 36672551, 2022). "Together with high level expression of HDAC1 and HDAC2 in human BCC samples, our findings therefore warrant further studies of 4SC‐202 and other class I HDACi as combination or second‐line drugs to tackle the problem of frequent SMOi‐resistance development observed in HH‐driven cancers such as BCC." (PMID 29055107, 2018). "Because HDAC1 and HDAC2 deacetylate H4K16 to promote DSB repair, it is tempting to speculate that the observed HDAC1/HDAC2 overexpression and hypoacetylated H4K16 in cancers could deregulate the DDR, resulting in genetic and epigenetic instability that would promote tumorigenesis." (PMID 27631103, 2016). "Perhaps not coincidentally, as the presented AD model suggests, HDAC2, whose elevated levels are commonly associated with neurodegenerative disorders, is an oncogene, whereas HDAC inhibitors are considered as a new promising class of anti-cancer drugs." (PMID 26041885, 2015). "Thus, we conclude that HDAC3 plays a distinct role from HDAC1 and HDAC2 during chromatin maturation and that targeting HDAC3 with small molecule inhibitors will provide additional therapeutic impact in the treatment of CTCL and other cancers." (PMID 23894374, 2013). "Moreover, we have noted that HDAC2 expression was gradually increased from non-tumor to overt cancer based on gene expression analysis of multi-step histopathological grades of HCC." (PMID 22132221, 2011). "It is tempting to speculate that an accumulation of NOXA due to an inhibition of HDAC2 and a disruption of the SIN3 complex combined with compromised genomic integrity due to an inhibition of HDAC3 are molecular mechanisms through which KH16 kills cancer cells." (PMID 37509312, 2023).
cancer (continued). "Furthermore, since p21 is dysregulated in some tumors, it could be interesting to further investigate the action of dex on the multicomplex protein assembly Lamin A/C, HDAC2, LAP2α, pRb, E2F1, and FoxO3a on the CDKN1A promoter that might regulate p21 expression, in some cancer cell types." (PMID 37345209, 2023). "However, the development of anti-cancer drugs targeting HDAC2 has not been successful." (PMID 36968022, 2023). "Therefore, it is possible that the pro-oncogenic function of HDAC2 may be dependent on the type of cancer, whereas the tumor-suppressive function of miR-489-3p may not be restricted to a specific cancer type." (PMID 32774482, 2020). "We further show that HDAC1 and HDAC2, but not LSD1, are responsible for RCOR2-dependent transcriptional suppression of CIITA in cancer cells." (PMID 40608411, 2025). "A growing body of evidence suggests that HDAC2-inhibiting drugs such as class I HDAC inhibitor, can act not only as standalone anti-cancer agents but also improve the therapeutic effect of ICIs in various types of solid cancers." (PMID 37716965, 2023). "Conversely, negative PD-L1 regulators (HDAC1, HDAC2, and HDAC3) seemed insignificant during cancer progression." (PMID 34830209, 2021). "Our demonstration that the administration of SAHA to wild type and R6/2 mice decreases the levels of HDAC2 and HDAC4 at the protein and not RNA levels extends previous observations in cancer cell lines to the in vivo situation." (PMID 22140466, 2011). "Although TRIB2 has been reported to modulate p38,34 p38 inhibition did not abrogate the anisomycin‐induced phosphorylation of HDAC2 in ESCC cells, suggesting that the effect of TRIB2 on the MAPK pathway might be cancer‐dependent." (PMID 34586732, 2021). "However, in BC, after MPA treatment, TRPS1 was identified as a transcription coactivator, PR recruited TRPS1 but did not interact with HDAC2 in the specific breast cell context, thus accelerating the acetylation of RANKL and enhancing the cancer-promoting effect of MPA." (PMID 37344459, 2023). "Unlike PD-L1 negative regulators (HDAC1, HDAC2, and HDAC3), the expression ranks of PD-L1 and its positive regulators (EP300, CREBBP, IRF-1, and BRD4) negatively correlated to Grade Group in another study, suggesting an increase of function during cancer progression." (PMID 34830196, 2021).
tumor (269 papers, 2006 to 2026). "We further demonstrated for the first time the distinct trends of associations between class I and class IIA HDACs and anti-tumor immunity, with the expression of class I HDAC2 being negatively correlated and class IIA HDAC7 being positively correlated." (PMID 39063083, 2024). "Several recent studies have reported that HDAC2-associated deacetylation promotes the nuclear translocation of PD-L1, leading to tumor immune evasion in BC cells." (PMID 37764768, 2023). "Higher levels of HDAC2 have also been associated with more aggressive tumor characteristics, such as increased cell proliferation, invasion, and metastasis." (PMID 37764768, 2023). "Similar to SAHA, RA inhibited cell growth and cancer spheroid formation, as well as causing tumor cell death and blocking HDAC2 expression." (PMID 35774546, 2022). "Our findings imply an inversely proportional association of HDAC-2 and -6 positivity with tumor differentiation grade." (PMID 33799478, 2021). "We had already observed that HDACi class I inhibit an EWS-FLI1-specific expression profile and that the elimination of HDAC1 and HDAC2 reduces the tumor susceptibility of EwS cells." (PMID 34654445, 2021). "Associations between HDAC1 or HDAC2 expression with neoadjuvant chemotherapy were evaluated by comparing HDAC1 or HDAC2 expression in pre-therapeutic tumour biopsies against histopathological tumour regression after treatment." (PMID 34439236, 2021). "Similar to the effects of SAHA, RA reduced cell growth and blocked cancer spheroid formation, caused the apoptosis of tumor cells, and blocked the expression of HDAC2." (PMID 32532056, 2020). "Higher levels of HDAC1 and HDAC2 expression are significantly associated with tumor differentiation." (PMID 29899271, 2018). "Tumour-suppressive functions of HDAC1/HDAC2 in the skin became evident when one allele of Hdac2 was eliminated in Hdac1 null mice." (PMID 29472538, 2018). "MYC causes overexpression of HDAC2, contributing to tumor cell proliferation, while inactivating mutations in HDAC2 reduce the frequency of tumors in mice." (PMID 28505071, 2017). "High rates of HDAC1 and HDAC2 expression were significantly associated with tumor dedifferentiation, and HDAC2 expression is associated with shorter PSA relapse time after radical prostatectomy." (PMID 28555004, 2017). "Previous studies reported that T cell-32, 33 and epidermal cell-34 specific ablation of Hdac1 and Hdac2 alleles unexpectedly leads to spontaneous tumor formation." (PMID 27886239, 2016). "We found that the combined treatment induced a proportional and significant decrease in HDAC2 expression level, which were associated with tumour shrinkage as measured by tumour size and luciferase activity." (PMID 27283986, 2016). "We observed a gradual decrease in tumor incidence and concomitant gradual increase in mean overall survival upon deletion of combinations of Hdac1 and Hdac2 alleles." (PMID 27886239, 2016). "BT147 was identified as the most sensitive line, possibly due to the presence of a point mutation in HDAC2 which was also detected in the original patient tumor." (PMID 27449082, 2016). "For this we generated B cell-specific deletions of different combinations of Hdac1 and Hdac2 alleles in vivo and monitored mice for tumor development over a period of 300 days by the Kaplan-Meyer (KPLM) method." (PMID 27886239, 2016). "To investigate the effect of loss of HDAC2 function on tumor biology, we performed siRNA-mediated knockdowns of HDAC2 in MYC amplified cells." (PMID 25853389, 2015). "It is known that the c-Myc/Skp2/Fbw7α and HDAC1/HDAC2 pathways, are associated with tumor progression." (PMID 24265759, 2013). "High rates of HDAC1 and HDAC2 expression were significantly associated with tumour dedifferentiation." (PMID 18212746, 2008). "In vitro assays exhibited that HDAC2‐mut abolished the tumor suppression caused by PJA2." (PMID 39928532, 2025).